IL4 (interleukin 4)
Diseases named in the same sentence as IL4 in open-access papers (continued):
Sharing a sentence is not in itself a finding about the gene and the disease.
asthma (continued). "These cells produce IL-21 and IL-4, which are essential for B-cell stimulation and play a key role in controlling IgE production in asthma." (PMID 37377958, 2023). "The results showed that the expression of miR-16, miR146-a and IL-4 levels in patients with asthma after receiving probiotic supplementation was significantly reduced and miR-133b expression was increased." (PMID 36593510, 2023). "Pascolizumab, an IL-4 depleting antibody is admitted for clinical intervention in moderate to severe asthma." (PMID 37881430, 2023). "For example, studies have shown the efficacy of biologicals targeting interleukin-5 (IL-5) and interleukin-4/13 (IL-4/13) in asthma and the effectiveness of nintedanib, a tyrosine kinase inhibitor, in slowing the progression of IPF." (PMID 37631365, 2023). "Pitrakinra, an Escherichia coli-derived IL-4 antagonist, has been evaluated in clinical trials for asthma treatment in the past; however, deficits such as short serum lifetime and potential immunogenicity among others stopped further development." (PMID 37483220, 2023). "IL-4 is secreted by activated Th2 cells and plays an important role in airway inflammation in asthma, It induces the maturation of B lymphocytes to produce IgE under the synergistic effect of IL-5." (PMID 37451839, 2023). "Several biological agents, including anti-immunoglobulin E, anti-interleukin-5, and anti-thymic stromal lymphopoietin/interleukin-4, have been approved for the treatment of severe asthma." (PMID 38203353, 2023). "For a long time, inflammatory diseases were thought to associate with either an IFNγ-driven Th1-type inflammatory response (e.g. multiple sclerosis) or a Th2-type response characterised by the expression of IL-4, IL-5 and IL-13 (e.g. asthma)." (PMID 35275333, 2023). "Based on accumulating evidence implicating IL-4, IL-5, and IL-13 are responsible for the occurrence and development of asthma." (PMID 37377958, 2023). "The novel immunologic agents (e.g., anti-IL-4 monoclonal antibody, anti-IL-5 monoclonal antibody, anti-IgE monoclonal antibody) are also useful in this type of asthma." (PMID 37090692, 2023). "IL-4 and IL-17 are critical inflammatory factors in asthma, and IFN-γ and IL-10 are essential anti-inflammatory factors." (PMID 36636604, 2023). "Asthma patients experience a higher regulation of Th2, which leads to an increase in the production of IL-4 cytokines." (PMID 37760982, 2023). "In asthma, an increase in C3 leads to innate lymphoid cell chemotaxis (ILC2), which ultimately raises the production of IL-4 and IL-13 and causes inflammation." (PMID 37422662, 2023). "In type 2-low asthma, the upregulation of T2 immune pathways (e.g., IL-4 and IL-13) and eosinophilic inflammation characteristic of type 2-high phenotype are classically absent, contributing to the poor response to corticosteroids." (PMID 37108417, 2023). "Through the case–control study, the distribution differences of the genotype frequencies and allele frequencies in the four SNP loci: ADRB2 rs1042713, IL4 rs2243250, FCER1B rs569108, IL13 rs20541in asthma group and control group." (PMID 38049812, 2023). "Th2 cytokines, including interleukin (IL)-5, IL-4, and IL-13 play a significant role in initiating the inflammatory cascade in asthma." (PMID 37063828, 2023). "Th2 cell-specific cytokines, including IL-4, -5, and -13, are the major players in the mechanism of allergic inflammation, and they have become major targets of asthma therapeutics." (PMID 37998734, 2023). "IL-4 plays important roles in asthma, it induces Ig isotype switching and the production of IgE through the activation of B cells and promotes the production of eosinophil and neutrophil via mast cell stimulation." (PMID 37891170, 2023). "Dupilumab is the first fully human anti-IL-4 receptor α monoclonal antibody approved for asthma that blocks both IL-4 and IL-13 signaling." (PMID 37377958, 2023).
asthma (continued). "The aim of this study was to investigate the improvement of clinical asthma symptoms and changes in the expression pattern of selective microRNAs in patients with asthma and the changes in IL-4 and IFN-γ plasma levels after receiving probiotics." (PMID 36593510, 2023). "Gene set enrichment analysis (GSEA) showed enrichment in asthma pathways, including increased IL-13, IL-4, and IL-5 expression." (PMID 37699899, 2023). "Interleukin (IL)-4, IL-5 and IL-13, plays a vital role in the pathophysiology of eosinophilicairway diseases such as asthma, chronic rhinosinusitis, eosinophilic granulomatosis with polyangiitis and hypereosinophilic syndrome." (PMID 37886149, 2023). "The synergistic action of IL-4, IL-5, and IL-6 can stimulate the change of IgA secretion and mediate delayed asthma reaction." (PMID 38077793, 2023). "Numerous asthma cases have reported increased interleukin-4 (IL-4) and interleukin-5 (IL-5 levels, eosinophils-mediated infiltration and activated mast cells." (PMID 38178983, 2023). "As sputum cytokines were not investigated as part of the BIOAIR study, we carried out an additional investigation into the relationship between sputum periostin with sputum IL-4 and IL-13 in a separate cohort of patients with asthma." (PMID 36763690, 2023). "Dupilumab is used to treat oral corticosteroid-dependent severe asthma because it inhibits IL-4, a key cytokine involved in the induction of corticosteroid resistance." (PMID 38067174, 2023). "IL-4 is of course a signature Th2 cytokine that plays a role in asthma and indeed, ES-62 has been previously shown to inhibit IL-4 responses in the acute ovalbumin-induced airway hyper-responsiveness model." (PMID 38077318, 2023). "Smirnova S.V., Smolnikova M.V., Konopleva O.S. Polymorphism ofgenes (IL4, IL5) as a genetic predisposition to asthma in children.Eur." (PMID 37465198, 2023). "This pathway is essential in the development of allergic asthma and is likely genetically controlled, evidenced by a polymorphism in the IL-4, IL-13, and RAD50 genes associated with asthma and atopy." (PMID 37265457, 2023). "Another significantly associated variant that belongs to the 5q31 locus is the IL4 rs2243248 SNP, where our REM reported the protective effect of the minor rs2243248 G allele in AD risk, similar to asthma." (PMID 37510360, 2023). "In type 2-high asthma, B cells produce IgE under the influence of the Th2 cytokines, IL-4 and IL-13." (PMID 36845128, 2023). "Following viral infections, concentrations of sputum IL-4 and IL-5 in the asthma subjects significantly increased up to day 3, and afterwards peaked on day 8 during the observation period." (PMID 37865742, 2023). "During asthma progression, IL-4 induces an isotype switch to IgE in memory IgG-positive B lymphocytes." (PMID 37107297, 2023). "JAK inhibitors are an attractive small molecule option given the widespread signaling of cytokines and growth factors using JAK-STAT receptors in asthma, including IL-4, IL-5, IL-13, GM-CSF, IFN-α, IFN-β, IFN-γ, and TSLP." (PMID 37265457, 2023). "T helper 2 cells (Th2), as a primary source of the type 2 cytokines IL-4, IL-5, and IL-13, capable of driving all these immunological and physiological features, have therefore long been considered central to asthma pathogenesis." (PMID 37163370, 2023). "The extract of O. basilicum leaves on animal model of asthma increased the IFN-γ/IL-4 ratio (Th1/Th2 balance) but decreased bronchoalveolar lavage fluid (BALF) levels of IgE, phospholipases A2 (sPLA2), and TP." (PMID 37275758, 2023). "IL-4 can regulate IgE expression level and promote IgE-mediated humoral lymphatic response, resulting in asthma." (PMID 38077793, 2023). "Lycopene exerts a therapeutic effect against asthma by reducing eosinophilic infiltrates and Th2-mediated cytokines IL-4 and IL-5 production in the airways." (PMID 37367073, 2023).
asthma (continued). "both the CT genotype of IL4 rs2243250 and the T alleleof IL13 rs1800925 were associated with both controlled anduncontrolled asthma, with the TT genotype of IL13 rs1800925being associated with with uncontrolled one." (PMID 37465198, 2023). "Another therapeutic agent targeting both IL-4 and IL-13, pitrakinra, a dual IL-4/IL-13 antagonist, reduced asthma exacerbations only in a subgroup of patients with specific gene polymorphisms of IL-4 receptor." (PMID 37199256, 2023). "The disrupted and leaky barrier in asthma is well-documented and a positive feedback loop of IL-4 and IL-13 contributes to this phenotype seen in patients with asthma." (PMID 37520564, 2023). "It is known that TNF-α, IL-4, and IL-13 release is triggered by IL-33 and drives the type 2 inflammatory pattern seen in asthma." (PMID 37153601, 2023). "Th2 cells secrete IL-4 and IL-5 and increase IgE levels and eosinophil numbers, which can trigger inflammation, leading to asthma." (PMID 37569643, 2023). "Omalizumab, an anti‐IgE monoclonal antibody in asthma, is now used routinely for the treatment of allergic bronchopulmonary aspergillosis, and further agents targeting IL‐4 and IL‐5 are being evaluated." (PMID 36403106, 2023). "Following upper respiratory viral infections, the levels of induced sputum IFN-γ in asthma patients were increased prior to Th2 cytokines IL-4 and IL-5." (PMID 37865742, 2023). "Unlike corticosteroids which target an unspecified range of cells, biological therapies specifically target inflammatory cytokines (IL-4, IL-5, and IL-13), of T2-high asthma." (PMID 38259298, 2023). "Conversely, both the COPD (0.80–0.64 pg/mL, p = 0.025) and asthma (0.06–0.05 pg/mL, p = 0.007) groups exhibited significantly lower levels of interleukin-4 (IL-4) and interleukin-6 (IL-6) in EBC following hydrogen inhalation." (PMID 37873771, 2023). "Most patients with asthma have T2 inflammation, characterized by cytokines (IL-4, IL-5, and IL-13) and inflammatory cells (eosinophils, mast cells, basophils, and IgE-producing plasma cells)." (PMID 38203353, 2023). "They found that mast cells produced significantly more IL-4 when cultured with asthma-derived-fibroblasts compared to controls, with a subsequent increase in fibroblast-derived procollagen proteins." (PMID 36911735, 2023). "Abnormal T-helper type 2 (Th2) inflammation is the most important pathological process in asthma, mediated by Th2 cytokines such as interleukin (IL)-5, IL-4, and IL-13." (PMID 37174726, 2023). "As rBmTI-A reduced the concentrations of IL-5, IL-10, IL-13, and IL-17A, CrataBL reduced the numbers of IFN-γ, IL-4, IL-5, IL-13, and IL-17 positive cells in the airways and alveolar walls; both studies used an asthma model." (PMID 37511021, 2023). "By blocking the shared receptor component for IL-4 and IL-13, dupilumab improves upper and lower airway outcome measures in patients with severe CRSwNP and comorbid asthma, as reported by the body of evidence." (PMID 37464395, 2023). "We found that serum CXCL9 levels increased with age in patients with asthma, whereas serum IL-4 and total IgE levels showed an inverse trend relative to CXCL9 levels." (PMID 37005469, 2023). "Th2 cells generate IL-4, which is crucial in promoting proinflammatory functions that contribute to asthma." (PMID 37760982, 2023). "Studies demonstrate that controlling Th2-type asthma is effective via the preparation of anti-IL-4/IL-13 antibodies." (PMID 37873538, 2023). "Th2 cells and the cytokines they secrete (IL-4, IL-5, IL-13, and IL-9) are responsible for most of the pathological changes seen in asthma." (PMID 37174726, 2023). "Derangements of Th cells are deeply involved in the pathogenesis of asthma, in which Th2-secreted cytokines such as IL-4, IL-5 and IL-13 promote the accumulation of eosinophils and Th17-produced IL-17 mediate neutrophil recruitment." (PMID 37449208, 2023).
asthma (continued). "In childhood asthma, an influx of pro-inflammatory IL-17, IL-3, and IL-4, as well as an increase of Th-17 cells and an imbalance of Th1/Th2 cells, are found responsible for the disease." (PMID 37239112, 2023). "Nonetheless, some evidence suggests a role of IL-4 in instigating inflammatory conditions such as dermatitis, asthma, and Kawasaki disease." (PMID 37888172, 2023). "Dupilumab is a monoclonal antibody that targets interleukin (IL)-4 and IL-13 for use in moderate to severe eczema, asthma, and nasal polyposis." (PMID 37426396, 2023). "Pharmacologically active IL-13 inhibitors, such as pitrakinra (an IL-4 mutant), tralokinumab, or the soluble IL-13Rα2, have already been clinically tested for the treatment of other diseases, such as asthma or in tumor therapy." (PMID 37629063, 2023). "The levels of IL-4 and IL-13 were also found to be higher in children with recurrent wheezing, with the highest levels observed in those with asthma." (PMID 37760982, 2023). "For example, anti-asthma monoclonal antibodies against pro-allergic immunoglobulin E (IgE), IL-5, IL-4, and IL-13 have been developed." (PMID 36865540, 2023). "Pendrin, as an anion transporter located at the apical side of airway epithelial cells, acts as a downstream effector of the IL-4/IL-13 signaling pathway and participates, e.g., in airway inflammation in asthma." (PMID 36768179, 2023). "Once stimulated, ILC2 and Th2 produce type 2 cytokines, including IL-4, IL-5, and IL-13, responsible for the main alterations present in asthma." (PMID 37947596, 2023). "IL-4 levels in stunted asthmatic children were significantly higher than those in controls, as they were influenced by both stunted growth and asthma." (PMID 37760982, 2023). "ALA has been demonstrated to drastically lower serum IgE concentration, attenuate Th2 cytokines, IL-4, IL-5, IL-13, and IL-18, and reduce NF-B activation by decreasing intracellular ROS levels in a mouse model of asthma with allergic airway inflammation." (PMID 37251328, 2023). "For this reason, there have been trials of developed biological anti-interleukin therapy in asthma-targeted IL-4, -5, and -13, with cases of success." (PMID 37765323, 2023). "Dupilumab, another drug directed on T2 inflammation mechanisms, was precisely directed to the IL-4 receptor, which is a molecule that can interact both with IL-4 and IL-13 (currently used in atopic dermatitis, nasal polyposis, and asthma)." (PMID 37765327, 2023). "IL-4 and IL-13 play a powerful and intricate role in the type 2 cytokine response due to their effect on nearly every cell relevant to asthma." (PMID 37265457, 2023). "A study conducted in Syria also reported increased levels of IL-4 in children with asthma compared with controls." (PMID 37760982, 2023). "The proportion of ADRB2 rs1042713 A allele, IL4 rs2243250 T allele, FCER1B rs569108 A allele, and IL13 rs20541 G allele in the asthma group was higher than those in the control group." (PMID 38049812, 2023). "Increasing the abundance of these genera can improve microbial dysbiosis, regulate the diversity of intestinal microbiota, reduce the levels of inflammatory factors, namely, IL-4, IL-5, and IL-13, and alleviate the development of asthma airway inflammation." (PMID 36636604, 2023). "Overweight/obesity modified the association between asthma and 3 of the proteins: fibroblast growth factor 21 (FGF21), interleukin 4 (IL‐4), and urokinase‐type plasminogen activator (uPA)." (PMID 36973952, 2023). "Dupilumab is a monoclonal antibody that blocks the receptor for IL-4 and IL-13 and is also approved for treating severe asthma with a predominance for type 2 inflammation." (PMID 37511254, 2023). "The central drivers of T2-high asthma are IL-4, IL-5, and IL-13 that drive airway inflammation through increasing eosinophils, basophils, and mast cells in the airways." (PMID 38259298, 2023).
asthma (continued). "From a pathophysiological view, both disorders, CRSwNP, and asthma share the same type 2 immunopathology (involvement of IgE, eosinophils, interleukin-4 (IL-4)/IL-13, and IL-5) and exhibit epithelial barrier dysfunction." (PMID 37464395, 2023). "The relevance of IL-4 and IL-13 in the pathophysiology of asthma has been extensively addressed throughout various studies and reports." (PMID 37199256, 2023). "Patients with mild and moderate asthma present a typical response, that is, helper T cell type 2 (Th2) inflammation, mediated by cytokines such as IL-4, IL-5 and IL-13, and eosinophilia." (PMID 35967383, 2022). "TH2 mediators, TNF-α, IL-5, IL-4, IL-1ß play primary role in coordinating various inflammatory mechanisms in asthma." (PMID 38143476, 2022). "In patients with moderate-to-severe asthma, the treatment with dupilumab, an anti-IL-4Rα antibody, efficiently reduces severe exacerbation and improves lung functions, suggesting the involvement of IL-4 and/or IL-13 in the pathogenesis of asthma." (PMID 35693800, 2022). "The current therapeutic approach for Th2-high severe asthma is based on biologics targeting allergy molecules (IgE) and eosinophilic interleukins (IL-5, IL-4, IL-13, TSLP)." (PMID 35887589, 2022). "TNF-α promotes the secretion of related inflammatory mediators (such as IL-4) to participate in the occurrence and development of asthma and is one of the important reasons for the persistence of airway inflammation." (PMID 35399628, 2022). "The immune function of asthma children and healthy children was evaluated by detecting IgE concentration, eosinophil count, IL-4, and IL-17A." (PMID 35356750, 2022). "KEGG enrichment analysis revealed that SYD mainly acted on asthma-related signaling pathways, with IL-4 and TNF-α being the main action targets in treating asthma." (PMID 36212941, 2022). "Accumulating evidence from ex vivo studies as well as AR or asthma animal models lend credence to the further assessment of IL-4/IL-13-targeted therapy in AR and asthma patients." (PMID 35663523, 2022). "Then, in the experiment of PEF against asthma, our findings showed that the expression of IgE, IL-4, IL-5, IL-6, IL-13, and IL-17 were significantly higher in the model group." (PMID 36172200, 2022). "Studies on asthma indicate that inhibiting the production of inflammatory factors, such as IL-1, IL-6, IL-8, IL-4, IL-5, TNF-α, and IFN-γ, can reduce allergic symptoms." (PMID 36307493, 2022). "Together, these two pathways lead to differentiation of naive T cells into Th2 cells, releasing a large number of inflammatory factors (IL‐4, IL‐5 and IL‐13) and aggravating the progression of asthma." (PMID 35079347, 2022). "GLP1 agonists were found to decrease eosinophilic secretion of interleukin 4, interleukin 8, and interleukin 13 in mice with asthma." (PMID 36457601, 2022). "IL-4 and IL-13 are main signature cytokines in type 2 immune response and are responsible for asthma and many other allergic inflammatory diseases." (PMID 35281601, 2022). "These patients require disease-modifying therapeutic agents such as targeted agents against IL-4/IL-13 that can shift the natural course of disease progression in AR and asthma." (PMID 35663523, 2022). "The blood serum IL-17 level in the Th17-dominant asthma group was significantly higher than that in the T2 asthma group, while the serum IL-4 level was significantly higher in the T2 asthma group." (PMID 36303542, 2022). "In a papain-induced asthma model, activated basophils produce IL-4 which promotes the proliferation of ILC2, enhances the production of IL-5 and CCL11 from TSLP-activated ILC2s, and facilitates recruitment of eosinophils into the lungs." (PMID 35693800, 2022). "An asthma cell model was established with interleukins (IL-4, IL-13 and IL-17A) and transfected with siRNA-CXCR1." (PMID 36575422, 2022).